SOCS2 (suppressor of cytokine signaling 2)
Diseases named in the same sentence as SOCS2 in open-access papers (continued):
Sharing a sentence is not in itself a finding about the gene and the disease.
liver cancer (continued). "All together, these results shown that downregulation of NR1H4 and SOCS2 might partly play a key role in promote liver cancer and they maybe used as potential new biomarkers for liver cancer diagnosis." (PMID 30787420, 2019). "METTL3 facilitates m6A modification of suppressor of cytokine signaling 2 (SOCS2) and promotes its mRNA degradation through a YTHDF2-dependent pathway, thereby regulating the progression of liver cancer." (PMID 40495163, 2025). "In liver cancer, METTL3 promotes the expression of SOCS2 through YTHDF2 dependent enhancement of SOCS2 m6A modification, which in turn induces lung metastasis of liver cancer." (PMID 40097750, 2025). "SOCS1 alterations through SOCS7 and CISH alterations were detected in liver cancer tissues at the following frequencies: SOCS1, 1.1%; SOCS2, 0.8%; SOCS3, 6%; SOCS4, 0.3%; SOCS5, 1.3%; SOCS6, 1.3%; SOCS7, 2.4%; and CISH, 2.7%." (PMID 39307915, 2024). "In liver cancer, METTL3 participates in RNA decay by facilitating the binding of m6A reader YTHDF2 to the SOCS2 gene, ultimately promoting cancer cell proliferation and migration." (PMID 38966069, 2024). "METTL3 was reported to promote liver cancer progression; mechanistically, METTL3 increased SOCS2 mRNA m6A abundance, leading to SOCS2 mRNA degradation, which was mediated by YTHDF2." (PMID 36009465, 2022). "It was demonstrated that suppressor of cytokine signaling 2 was the target of METTL3-mediated m6A modification and METTL3 repressed its expression through an m6A-YTHDF2-dependent pathway in liver cancer." (PMID 35280730, 2022). "METTL14 promotes SOCS2 expression to inhibit the progression of liver cancer, while METTL3 inhibits SOCS2 expression in a YTHDF2-dependent manner, but whether METTL3 regulates the metabolism of HCC through SOCS2 requires more direct evidence." (PMID 38560499, 2024). "Analysis based on TCGA database indicated that NR1H4 and SOCS2 were downregulated in liver cancer, this suggest NR1H4 and SOCS2 may play an important role in tumorigenesis." (PMID 30787420, 2019). "In liver cancer, multiple different groups’ investigations showed that METTL14 inhibits EMT, invasion and metastasis of liver cancer cells by regulating m6A-modified target mRNAs such as EGFR/PI3K/AKT, DGCR8/primiR-126, USP48/SIRT6/glycolysis, CSAD, GOT2 and SOCS2." (PMID 40734692, 2025). "Eventually, a four-gene (karyopherin subunit alpha 2(KPNA2), suppressor of cytokine signaling 2(SOCS2), GTP-binding protein 4(GTPBP4), and chromobox 2(CBX2)) signature model was constructed by multivariate analysis showing that they were independent prognostic factors for liver cancer." (PMID 35479398, 2022).
breast carcinoma (30 papers, 2007 to 2025). "SOCS2 is hypermethylated in ovarian and breast cancers, in which its reduced expression is associated with the activation of STAT3, indicating an increased cytokine responsiveness in these tumors." (PMID 24280133, 2014). "Similar to our observations in breast cancer low SOCS2 expression in prostate cancer is associated with an increased incidence of metastasis and SOCS2 mRNA levels decrease during prostate cancer progression." (PMID 17651480, 2007). "Loss of SOCS2 might be associated with cell proliferation, tumor growth, and a poor prognosis in breast carcinoma." (PMID 33397365, 2021). "Studies have shown a decreased expression of SOCS2 gene in diabetic patients, and there exists a correlation between diabetes and hypertension; we suggest a that a downregulation of this gene in breast cancer patients may predispose them to a hypertensive phenotype." (PMID 38895458, 2024). "According to, breast cancer patients with a higher expression of SOCS2 gene significantly lived longer than those with a lower expression profile." (PMID 38895458, 2024). "In our study, we observed the downregulation of SOCS2 gene, suggesting a more aggressive tumor among breast cancer Kenyan women." (PMID 38895458, 2024). "Several studies have reported a correlation between the downregulation of SOCS2 gene and breast cancer pathogenesis." (PMID 38895458, 2024). "Low expression of SOCS2 leads to dysregulation of the breast cancer cell cycle and promotes breast cancer cell growth." (PMID 38071211, 2023). "Suppressor of cytokine signaling 2 (SOCS2) is one of the key proteins that regulates cytokine responses and has been reported to be down-regulated in tumors, such as breast cancer and ovarian cancer." (PMID 37085288, 2023). "Previous studies have found that SOCS2 plays an anti-tumor role in breast cancer and colon cancer, while it acts as a pro-cancer factor in chronic myeloid leukemia." (PMID 38071211, 2023). "In an analysis of 1109 breast cancer samples and 113 normal breast samples, SOCS2 and SOCS3 showed lower expression levels in cancer tissues than in normal tissues, and patients with high expression of SOCS2, SOCS3 and SOCS4 exhibited better outcome." (PMID 35884417, 2022). "SOCS2 expression, which was inhibited by exosomal miR-3613-3p promotes proliferation, metastasis, and drug resistance of breast cancer cells, and SOCS2 is expressed at low levels in breast cancer tissues." (PMID 35037826, 2022). "SOCS2 inhibition was found to promote progression and metastasis in colorectal, prostate, and breast cancers, whereas it inhibits the progression and metastasis of ovarian and gastric cancer." (PMID 35037826, 2022). "STAT3 hyperactivation was also reported to correlate with SOCS2 silencing in ovarian and breast cancers." (PMID 34589421, 2021). "In 2020, the same group focused on another CAF-released miRNA, miR-3613-3p, demonstrating its role as oncogene, promoting breast cancer drug resistance, ROS production and metastasis through the inhibition of suppressor of cytokine signaling 2 (SOCS2)." (PMID 34359591, 2021). "Based on the ROC curve analysis results, the SOCS1 and SOCS2 expression levels had the best specificity and sensitivity values respectively for breast cancer diagnosis." (PMID 30453988, 2018). "The SOCS1 and SOCS2 expression levels had the best specificity and sensitivity values respectively for breast cancer diagnosis." (PMID 30453988, 2018). "Previous studied have revealed that SOCS2 was downregulated in ovarian, breast carcinomas, pulmonary adenocarcinoma and HCC39–42." (PMID 28717245, 2017). "In contrast, SOCS2 expression was shown to have a favourable prognostic value in breast cancer, and hypermethylation of SOCS2 was detected in ovarian but not breast cancer." (PMID 24757565, 2014). "This is the first report on the favorable prognostic value of high SOCS2 expression in primary mammary carcinomas." (PMID 17651480, 2007).
breast carcinoma (continued). "The present study is aimed to elucidate the clinicopathological features associated with SOCS1, SOCS2, SOCS3, CIS and IGF-I expression in breast cancer." (PMID 17651480, 2007). "There, in primary mammary carcinoma immunohistochemical staining of SOCS2 correlated with SOCS2 mRNA expression." (PMID 17651480, 2007). "In conclusion, the current data do not support methylation as a major factor contributing to differences in SOCS2 expression levels in primary breast cancers." (PMID 17651480, 2007). "In addition, increased miR-3613-3p expression was shown to promote proliferation and metastasis in breast cancer cells by targeting SOCS2." (PMID 39796161, 2025). "We identified downregulation of the SOCS2 gene among Kenyan breast cancer patients." (PMID 38895458, 2024). "A study by observed that the expression of SOCS2 inhibits the growth of breast cancer cells." (PMID 38895458, 2024). "SOCS3 may be a factor in the prognosis of breast cancer patients, while SOCS2 may be a potential therapeutic target." (PMID 39307915, 2024). "SOCS2 showed a gain of DNA methylation and downregulated expression in breast cancers." (PMID 35739271, 2022). "A previous report demonstrated that high SOCS2 expression could serve as an independent predictor for favorable prognosis in breast cancer." (PMID 33397365, 2021). "The expression of SOCS2 in breast cancer decreased with the increase of tumor grade." (PMID 33414813, 2020). "High SOCS2 expression was an independent predictor of good prognosis in breast cancer." (PMID 33414813, 2020). "SOCS2 was found to be expressed in both normal/benign breast tissue and breast cancer specimens." (PMID 20433750, 2010). "Preliminary results from MCF7 mammary carcinoma cells show that overexpression of SOCS2 results in a significant reduction of anchorage independent growth, which supports the hypothesis of SOCS2 as an antioncogene." (PMID 17651480, 2007). "This is the first report on the prognostic significance of SOCS2 expression in breast cancer." (PMID 17651480, 2007). "Our results point to the hypothesis that both IGF-I and SOCS2 expression in breast cancer is controlled by similar mechanisms." (PMID 17651480, 2007). "Moreover, circ-NOL10 sponges miR-767-5p in breast cancer (BC) to promote the expression of suppressors of cytokine signaling 2 (SOCS2) and attenuate janus kinase 2/signal transducer and activator of transcription 5 (JAK2/STAT5) signaling, therefore preventing cancer progression." (PMID 37587156, 2023). "Therefore, we speculated that low expression of SOCS2 may promote breast cancer progression through regulation of STAT5A." (PMID 34120621, 2021). "SOCS3 may be a prognostic factor, and SOCS2 may be a potential therapeutic target in breast cancer." (PMID 34120621, 2021). "SOCS2 expression was also higher among those who remained disease free compared to all other patients who developed any type of recurrence (local or distant) or died from breast cancer during the same follow up period [mean copy number 360706 vs. 16359, 95% CI (40447, 648249), p = 0.027]." (PMID 20433750, 2010). "The correlation analysis between clinical data from breast cancer patients and the expression levels of JAK-STAT genes revealed a positive correlation between the SOCS2 gene and heart rate." (PMID 38895458, 2024). "We determined the mRNA expression levels of SOCS1, SOCS2, SOCS3, CIS and IGF-I in 89 primary breast cancers by reverse transcriptase PCR." (PMID 17651480, 2007). "We further compared the mRNA expression of SOCS2 and IGF-I in primary breast carcinomas (CA) and the corresponding normal adjacent tissue (TA) in a set of seven tumors." (PMID 17651480, 2007). "The mRNA content of SOCS1, SOCS2 and IGF-I was assessed in 89 primary breast cancer samples, and of SOCS3 and CIS in 64 samples." (PMID 17651480, 2007).
breast carcinoma (continued). "In this study, we therefore sought to elucidate the relationship between pathological and clinical parameters and the expression of the SOCS family members SOCS1, SOCS2, SOCS3, and CIS in patients with breast cancer by RT-PCR." (PMID 17651480, 2007). "Research shows that the expression levels of SOCS1, SOCS2, and SOCS3 are different in breast cancer tissue, which may be related to the heterogeneity of breast cancer tissue." (PMID 39307915, 2024). "SOCS2 is upregulated by 17β-estradiol in cancer cell lines, and SOCS2 expression was found to be higher in breast carcinomas compared to non-diseased breast tissue." (PMID 21625632, 2011). "Furthermore, our results show decreased SOCS2 and 3 expressions with increased Nottingham Prognostic Index (NPI) which adds significant positive prognostic role of these proteins in breast cancer." (PMID 20433750, 2010). "To evaluate the potential significance of SOCS expression in mammary carcinoma for prognosis and its association with clinicopathological characteristics we have investigated the mRNA levels of SOCS1, SOCS2, SOCS3 and CIS in a representative collection of primary breast cancers specimens." (PMID 17651480, 2007). "Similar, unpublished results from our group show no significant CpG island methylation in SOCS2 locus in a limited number of breast cancer samples (Haffner MC and Auer D, unpublished data)." (PMID 17651480, 2007). "Furthermore, if confirmed in larger studies, determination of SOCS2 and IGF-I expression levels could be used in clinical decision making for patients with breast cancer." (PMID 17651480, 2007). "Furthermore, an association with various estrogen-dependent genes such as ANXA1, PIWIL2, CASP4, ESR1/ESR2, PLAC1, and SOCS2, has been shown in breast cancer—however, up to date, no such data concerning adenocarcinomas of the esophagogastric junction have been published." (PMID 31467538, 2019). "In 48 primary breast cancer samples no methylation was observed and only 13% of tumors showed LOH in the SOCS2 locus." (PMID 17651480, 2007).
prostate carcinoma (16 papers, 2007 to 2024). A carcinoma that arises from epithelial cells of the prostate gland. "On the other hand, elevated SOCS2 levels were found in colon and prostate cancer and were associated with a poor prognosis in the latter." (PMID 34029637, 2021). "The low expression of SOCS2 in primary prostate tissue was associated with an increased incidence of postoperative metastasis and decreased SOCS2 levels during prostate cancer." (PMID 33414813, 2020). "Oncogenic roles of SOCS2 were also reported in other tumor entities: SOCS2 levels were elevated in colon and prostate cancer, and high SOCS2 expression was associated with a poor prognosis in the latter." (PMID 31235852, 2019). "High SOCS2 expression is found in androgen-stimulated prostate cancer cells and is associated with pro-proliferation." (PMID 29622769, 2018). "In prostate cancer, on the other hand, hsa-miR-194-5p is increased and downregulates SOCS2 to promote cancer development." (PMID 38342922, 2024). "In our study, we develop and validate a prognostic signature (named TILTregSig) composed of five Treg-specific mRNAs (SOCS2, EGR1, RRM2, TPP1, and C11orf54) for prostate cancer, which is associated with RFS in prostate cancer." (PMID 35812443, 2022). "Downregulation of SOCS2 was an independent predictor of shorter biochemical recurrence-free survival for prostate cancer patients." (PMID 35812443, 2022). "SOCS2 is highly upregulated in androgen-induced prostate cancers and has been shown to promote cancer cell growth, with a reduction in SOCS2 levels inhibiting cell proliferation and xenograft growth." (PMID 34857742, 2021). "SOCS2 is an androgen-regulated gene and elevated levels in prostate cancer are consistently observed in independent patient cohorts." (PMID 29622769, 2018). "We previously observed that SOCS2 acts as a tumour suppressor in advanced castration-resistant prostate cancer." (PMID 28216640, 2017). "The results demonstrate that the EGR1 exhibited the highest mutation frequency followed by RRM2 and TPP1, while both SOCS2 and C11or54 do not show any mutations in prostate cancer samples." (PMID 35812443, 2022). "Furthermore, upregulation of SOCS2 is recognized as a potential prognostic marker for prostate cancer." (PMID 35186733, 2022). "Moreover, SOCS2 seems to have a dual effect in prostate cancer." (PMID 33397365, 2021). "Hence SOCS2 deficiency may lead to increased levels of NDR1, which results in aggressive behavior of PC3 prostate cancer cells." (PMID 31182716, 2019). "Also, upregulation of SOCS2 is recognized as a potential marker for prostate cancer prognosis." (PMID 29622769, 2018). "An F3-mimick that enhanced SOCS2 activity has the potential to reduce JAK/STAT and NF-κB-driven pulmonary inflammation, and in particular, may benefit cancer patients with HCC or prostate cancer." (PMID 34857742, 2021).
lung cancer (15 papers, 2018 to 2026). A malignant neoplasm involving the lung. "Loss of their function increases the GH-induced signaling in favor of aging and certain chronic diseases, exemplified by increased lung cancer risk in case of a mutation in the SOCS2-GHR interaction site." (PMID 33312162, 2020). "For lung cancer, a KM Plotter tool showed a correlation between low SOCS2 expression and poor overall survival." (PMID 37246269, 2023). "Previously, SOCS2 was reported to inhibit proliferation and promote the apoptotic phenotype in lung cancer." (PMID 35037826, 2022). "Downregulation of SOCS2 by different miRNAs has been found to promote proliferation, migration, and metastasis, and decrease apoptosis of lung cancer cells." (PMID 35037826, 2022). "Hsv2-miR-H9-5p increases lung cancer cell migration and invasion in vitro by directly targeting suppressor of cytokine signaling 2 (SOCS2), inhibiting Jak2 kinase activity and Jak2-signal transducer and activator of transcription 3 (STAT3) binding." (PMID 30813457, 2019). "According to relative SOCS2 expression in lung cancer tissues, the 1882 patients were classified into two groups: the high SOCS2 group (n = 909) and the low SOCS2 group (n = 973)." (PMID 29559623, 2018). "In lung cancer models, ALKBH5 regulates the circRNA echinoderm microtubule-associated protein-like 4 (circEML4)/miRNA/suppressor of cytokine signaling 2 (SOCS2) axis, supporting the M2-like function of tumor-associated macrophages and facilitating immune evasion in non-small cell lung cancer." (PMID 41376856, 2026). "In contrast, in lung cancer, SOCS2 is involved in a complex regulatory network." (PMID 35037826, 2022). "Additionally, downregulation of SOCS2 leads to enhanced proliferation and reduced apoptosis in lung cancer." (PMID 32437330, 2020). "Therefore, we hypothesized that miR-3648 may regulate lung cancer cell phenotypes by targeting SOCS2." (PMID 35037826, 2022). "For example, METTL3-mediated m6A modification destabilizes SOCS2 mRNA in HCC and BATF2 mRNA in gastric cancer and promotes the translation of epidermal growth factor receptor (EGFR) and the Hippo pathway effector TAZ in human lung cancer cells." (PMID 35456475, 2022).